PDCD10 (programmed cell death 10)
Diseases named in the same sentence as PDCD10 in open-access papers (continued):
Sharing a sentence is not in itself a finding about the gene and the disease.
cancer (continued). "We found that genetic overexpression of PDCD10 (OE-PDCD10) increased cancer metastasis by down-regulating E-cad and enhancing Vimentin (VIM) thereby inducing EMT and promoting β-catenin/Wnt-mediated cell migration." (PMID 32483426, 2020). "Future genetic and cellular studies of the spatiotemporal organization of PDCD10/STKs complexes under physiological conditions in various cell types will be needed to determine the precise function of PDCD10 in cancer cell migration and metastasis." (PMID 30408026, 2018). "Yet, it is unclear if cancer cells have hijacked different pathways other than the PDCD10-STK-ERM axis for their own benefits to support growth and migration." (PMID 30408026, 2018). "Inhibition of miR‐425‐5p increases sensitivity to anti‐cancer drugs by regulating apoptosis‐related protein PDCD10 both in vitro and in vivo." (PMID 26647742, 2016). "Aberrant expression of PDCD10 gene transcription has previously been detected in various types of human cancers." (PMID 26490252, 2015). "In addition to its role in cancer, PDCD10 also influences the Notch signaling pathway a critical regulator of cellular destiny, differentiation, and intercellular communication." (PMID 38351531, 2024). "In cancers, PDCD10 shows multiface functions in a context-dependent manner." (PMID 39273014, 2024). "To understand whether this finding is also conserved across other cancer types, we used the entire Cancer Cell Line Encyclopedia mRNA expression dataset to obtain the co-expression of all the pairwise combinations of C4orf19, PDCD10, STK24, STK25, and STK26." (PMID 38517886, 2024). "However, it is demonstrated that the expression of PDCD10 vary based on the specific type of cancer cell and the anti‐cancer drug utilized." (PMID 38351531, 2024). "However, PDCD10 is a multifaceted regulator in cancer due to its different subcellular localization and various protein interactor." (PMID 37781039, 2023). "Moreover, designing and developing effective inhibitors of PDCD10 will be a promising treatment strategy for some cancer types." (PMID 36497468, 2022). "Additionally, the role of PDCD10 in the modulation of immune cells in cancer is also emerging in other cancer types." (PMID 36497468, 2022). "Recently, growing amounts of studies have focused on function of PDCD10 in cancers." (PMID 36497468, 2022). "Due to its functional complexity, PDCD10 exhibits different effects in cancers." (PMID 36497468, 2022). "In the majority of cancer types, PDCD10 seems to promote oncogenesis." (PMID 36497468, 2022). "In cancers, interactions between PDCD10 and its interactors appear more complex." (PMID 36497468, 2022). "Furthermore, PDCD10 silencing promoted the apoptosis and decreased proliferation of malignant T cells, which is the first to link PDCD10 to cancer." (PMID 36497468, 2022). "This study could serve as a reference for the development of PDCD10 into a therapeutic target in cancers in the future." (PMID 36276268, 2022). "Based on the findings, we hypothesized that PDCD10 is an oncogene in many cancer types and thus may be employed as a prognostic marker." (PMID 36276268, 2022). "In this review, we provided an overview of the structure and molecular functions of PDCD10, and summarized the knowledge of the dual role of PDCD10 in cancers, with a view to future development and application of PDCD10 as a clinical therapeutic target in cancers." (PMID 36497468, 2022). "As a first step, we used the TIMER2.0 database to examine PDCD10 expression in cancers." (PMID 36276268, 2022). "Further details on the roles of PDCD10 in cancers will be discussed in the next section." (PMID 36497468, 2022). "In addition, we used information from single-cell sequencing data to evaluate the state of cancer cells in relation to PDCD10." (PMID 36276268, 2022). "More recently, the role of PDCD10 in malignant tumors has been emphasized." (PMID 32850441, 2020).
cancer (continued). "Similarly, PDCD10, a predicted miR-23b target, has been shown to play a dual role in cancer cell drug resistance." (PMID 31810268, 2019). "In line with the crucial role of PDCD10 in angiogenesis, vessel permeability and apoptosis and based on the altered expression of PDCD10 in various cancers, we assumed that PDCD10 could be potentially involved in the pathology of GBM." (PMID 26490252, 2015). "In contrast to the well-established function of PDCD10 in vasculogenesis, neo-angiogenesis, vessel remodeling and vessel permeability, only limited information is available on PDCD10 in malignant tumors despite its original description as an apoptosis related gene." (PMID 26490252, 2015). "However, the function of the homodimerization of PDCD10 is currently unclear in cancers." (PMID 36497468, 2022). "However, the precise molecular mechanism through which PDCD10 contributes to cancer remains unknown." (PMID 36276268, 2022). "However, there was remarkable controversy regarding the role of PDCD10 in human malignant tumors." (PMID 34108959, 2021). "Therefore, a therapeutic intervention that interrupts the functional SNAI2/miR-222-3p/PDCD10 axis might provide a promising strategy to treat EOC cancer." (PMID 32483426, 2020). "Indeed, an altered expression of PDCD10 was found in response to different chemotherapies, giving rise to the hypothesis that PDCD10 is involved in chemoresistance in certain cancers." (PMID 26490252, 2015). "Biochemical studies have reported that programmed cell death 10 (PDCD10) is a component of the striatin-interacting phosphatase and kinase (STRIPAK) complex and plays a dual role in cancers in a tissue- or disease-specific manner." (PMID 35963638, 2022). "Collectively, PDCD10 promotes EMT and the progression of HCC by interacting with PP2Ac to promote YAP activation, which provides new insight into the mechanism of cancer metastasis." (PMID 34521817, 2021). "We performed qPCR analysis of SNAI2, miR-222-3p and PDCD10 expression levels in 38 specimens of EOC patients collected from Hunan Cancer Hospital, and observed a strong correlation between SNAI2 and PDCD10 expression levels." (PMID 32483426, 2020). "Several studies of PDCD10 in CCM and cancers have been reported before." (PMID 35848121, 2023). "On the other hand, PDCD10 was also reported to stabilize GCKIII kinases and facilitate their translocation to sites of actomyosin, which promotes cell contraction and the metastasis of cancer cells." (PMID 36497468, 2022). "PDCD10 inhibits RhoA/ROCK signaling, thus promoting cancer cell survival and metastasis." (PMID 32226386, 2020). "Our study of the mechanisms by which TRIM59 controls cell plasticity through regulating PDCD10 stability and the downstream RhoA-ROCK signaling may provide novel insights into the regulatory network of cancer cell invasion and metastasis." (PMID 30408026, 2018). "Overexpression of miR-103 has been found in several type human cancers and previous studies reported that miR-103 could enhance the proliferation, migration, and invasion of cancer cells by targeting anti-oncogenes DICER and PTEN, TIMP-3, PDCD10, KLF4 respectively." (PMID 28445396, 2017).
genetic disease (4 papers, 2016 to 2026). "As a human genetic disease, three genes have so far been identified, whose loss-of-function mutations cause CCM disease: KRIT1 (CCM1), CCM2, and CCM3 (PDCD10)." (PMID 36831015, 2023).
brain disease (2 papers, 2007 to 2009). "Apart from the PDCD10-SERPINI1 gene pair at chromosome 3q26, there was another human head-to-head gene pair found to be associated with brain diseases." (PMID 17212813, 2007). "Here we present evidence that two non-homologous brain diseases-related genes, SERPINI1 and PDCD10, are tightly linked in a divergent configuration by a bidirectional promoter in an evolutionarily conserved fashion." (PMID 17212813, 2007). "Besides, there are evidences indicating that PDCD10 and SERPINI1 are both related to brain diseases." (PMID 17212813, 2007).
autosomal dominant disease (1 paper, 2022). Autosomal dominant form of disease. "CCM has been shown to be an autosomal dominant disease with incomplete penetrance, predominantly associated with mutations in 3 CCM genes (CCM1, CCM2, and CCM3/PDCD10)." (PMID 36497468, 2022).
kidney diseases (1 paper, 2021). "The identification of upstream signaling of PDCD10 and/or mutations or polymorphism in PDCD10 and STK genes associated with human kidney diseases may shed light on their potential roles." (PMID 34156031, 2021).
PDCD10 also shares sentences with these, for which no sentence is quoted: endothelial dysfunction (4 papers); Stroke (3); bacterial infection (2); Brain hemorrhage (2); cardiovascular diseases (2); hemorrhagic stroke (2); Hypertension (2); infection (2); non-small cell lung carcinoma (2); pancreatic adenocarcinoma (2); vascular malformation (2); acute myeloid leukemia (1); adenocarcinoma (1); adrenocortical carcinoma (1); angiomas (1); bladder urothelial carcinoma (1); bone tumor (1); cervical cancer (1); developmental venous anomaly (1); epilepsy (1); esophageal adenocarcinoma (1); gastric cancer (1); head and neck squamous cell carcinoma (1); hemimegalencephaly (1); hepatic angiosarcoma (1); intrahepatic cholangiocarcinoma (1); ischemic stroke (1); kidney chromophobe carcinoma (1); Leukoencephalopathy (1); liver cancer (1).
A further 15 diseases each share a sentence with PDCD10 in 1 paper.